PPP1R21 (protein phosphatase 1 regulatory subunit 21)
Description:
Component of the FERRY complex (Five-subunit Endosomal Rab5 and RNA/ribosome intermediary). The FERRY complex directly interacts with mRNAs and RAB5A, and functions as a RAB5A effector involved in the localization and the distribution of specific mRNAs most likely by mediating their endosomal transport. The complex recruits mRNAs and ribosomes to early endosomes through direct mRNA-interaction. In the complex, PPP1R21 serves as a binding hub connecting all five complex subunits and mediating the binding to mRNA and early endosomes via RAB5A. Putative regulator of protein phosphatase 1 (PP1) activity. May play a role in the endosomal sorting process or in endosome maturation pathway (Probable).
Synonyms: Fy-2; CCDC128; FERRY2; KLRAQ1; FLJ16566; NEDHFBA
Tractability: PROTAC: ubiquitination databases record sites on it; its protein half-life has been measured.
Gene: Protein-coding gene on chromosome 2 (48,440,598 to 48,515,391, forward strand). Ensembl gene ENSG00000162869.
Subcellular location: Early endosome
Subcellular location (Human Protein Atlas): Vesicles; Nucleoplasm
Gene Ontology:
Molecular function: mRNA binding; protein binding; protein-macromolecule adaptor activity; RNA binding
Biological process: regulation of intracellular mRNA localization
Cellular component: early endosome; early endosome membrane; membrane
Genetic constraint (gnomAD): Loss-of-function variants: 66 observed, 78.71 expected, observed/expected ratio (o/e) 0.84, 90% interval 0.69 to 1.03. The upper end of that interval is the gene's LOEUF score, 1.03, which puts it in group 4 of 6, group 1 being the genes least tolerant of losing a copy. Missense variants: 915 observed, 719.83 expected, observed/expected ratio (o/e) 1.27, 90% interval 1.2 to 1.34. Synonymous variants: 296 observed, 262.71 expected, observed/expected ratio (o/e) 1.13, 90% interval 1.02 to 1.24.
Gene-disease validity (ClinGen):
ClinGen rates the evidence that PPP1R21 causes each of these diseases.
neurodevelopmental disorder with hypotonia, facial dysmorphism, and brain abnormalities (autosomal recessive): Strong.
Homologues: Orthologues: chimpanzee PPP1R21 (99% identical), macaque PPP1R21 (99% identical), dog PPP1R21 (96% identical), pig PPP1R21 (95% identical), rabbit PPP1R21 (95% identical), rat Ppp1r21 (93% identical), guinea pig PPP1R21 (92% identical), mouse Ppp1r21 (92% identical), tropical clawed frog ppp1r21 (75% identical), zebrafish ppp1r21 (49% identical), Caenorhabditis elegans F33E11.3 (24% identical), Drosophila melanogaster CG6607 (18% identical).
Diseases named in the same sentence as PPP1R21 in open-access papers:
PPP1R21 is named in the same sentence as 19 diseases in open-access papers, as found by Europe PMC text mining. Sharing a sentence is not in itself a finding about the gene and the disease. The quoted sentences say what the papers report.
breast carcinoma (3 papers, 2024 to 2025). "According to the previously obtained data, susceptibility to breast cancer is determined by the rs10454142 PPP1R21, and predisposition to endometriosis was determined by the rs440837 ZBTB10." (PMID 41010401, 2025). "According to the findings from our previous work, the risk of developing breast cancer was influenced by rs10454142 PPP1R21, while the likelihood of developing endometriosis was determined by rs440837 [A/G] ZBTB10." (PMID 40724651, 2025).
endometriosis (3 papers, 2025). The growth of functional endometrial tissue in anatomic sites outside the uterine body. "Endometriosis-associated SNP-SNPinter models include 7 SNPs from 9 analyzed loci, such as rs17496332 (A > G) PRMT6, rs780093 (C > T) GCKR, rs10454142 (T > C) PPP1R21, rs3779195 (T > A) BAIAP2L1, rs440837 (A > G) ZBTB10, rs7910927 (G > T) JMJD1C, and rs8023580 (T > C) NR2F2." (PMID 41373783, 2025).
Developmental Delay (2 papers, 2023 to 2025). "Patients with mutations in PPP1R21 commonly experience global developmental delay, hypotonia, respiratory and feeding difficulties, and dysmorphic facial features." (PMID 40062705, 2025). "Over the last three years, homozygous variants in PPP1R21 have been described in 11 patients, most of them sharing developmental delay/intellectual disability, hypotonia, distinctive facial features, and brain anomalies." (PMID 36692708, 2023). "Mutation of PPP1R21 is associated with global developmental delay and hypotonia." (PMID 40062705, 2025).
Intellectual disability (2 papers, 2023 to 2025). "One case report of an adult patient with PPP1R21-related intellectual disability describes the patient's facial dysmorphism worsening with age." (PMID 40062705, 2025). "Mutation of TBCK causes TBCK syndrome, mutation of PPP1R21 is associated with PPP1R21-related intellectual disability, and mutation of FERRY3 results in an autosomal recessive intellectual disability." (PMID 40062705, 2025). "Only TBCK syndrome and PPP1R21-related intellectual disability share the presence of seizures, reduced reflexes, feeding and respiratory difficulties, and notable MRI characteristics, including white matter and ventricular abnormalities." (PMID 40062705, 2025). "Of the three disorders, TBCK syndrome and PPP1R21-related intellectual disability share the most similar clinical features." (PMID 40062705, 2025). "Our review identified 66 published descriptions of TBCK syndrome, 24 published descriptions for PPP1R21-related intellectual disability, and 16 published descriptions of FERRY3 autosomal recessive intellectual disability." (PMID 40062705, 2025). "Most information comes from case reports of patients with PPP1R21-related intellectual disability." (PMID 40062705, 2025).
Stroke (2 papers, 2019 to 2023). Sudden impairment of blood flow to a part of the brain due to occlusion or rupture of an artery to the brain. "In our study, PPP1R21 was identified as a hub gene in the outcome-associated co-expression module at 5 h after stroke." (PMID 36691064, 2023). "Moreover, the intronic variant rs1842681 is a trans-eQTL for PPP1R21, implicated in brain plasticity and outcome after stroke." (PMID 36691064, 2023).
thyroid cancer (2 papers, 2024 to 2025). "Multitudinous previously conducted clinical and experimental studies have shown that the association of PPP1R21 (PPP1R21) with the development of various tumors, including such as colorectal carcinoma, oral cancer (in mice), thyroid carcinoma, lung cancer, small intestine tumor, and stomach cancer." (PMID 38396861, 2024).
colorectal cancer (1 paper, 2024). A primary or metastatic malignant neoplasm that affects the colon or rectum. "Attention is drawn to the presence of evidence of the involvement of PPP1R21 in oncogenesis (colorectal cancer) in genome-wide studies." (PMID 38396861, 2024).
Obesity (1 paper, 2024). Accumulation of substantial excess body fat. "In our study, we detected an obesity-dependent association of the rs10454142 PPP1R21 with BC in women." (PMID 38672173, 2024). "In conclusion, our study detected an obesity-dependent association of the rs10454142 PPP1R21 with BC in women." (PMID 38672173, 2024). "We found that the BC-risk effect correlated by GWAS with the SHBG-level polymorphism rs10454142 PPP1R21 depends on the presence/absence of obesity." (PMID 38672173, 2024).
cancer (3 papers, 2024 to 2025). A tumor composed of atypical neoplastic, often pleomorphic cells that invade other tissues. "The risk genetic factor for BC developing is an SHBG-lowering allele variant C rs10454142 PPP1R21 ([additive genetic model] OR = 1.31; 95%CI = 1.08–1.65; pperm = 0.024; power = 85.26%), which determines 0.32% of the cancer variance." (PMID 38396861, 2024). "It is very interesting that two polymorphisms (rs10454142 PPP1R21 and rs4149056 SLCO1B1) out of eight BC-associated loci are likely drivers of the occurrence of tumors (“likely cancer driver”) (prognostic estimates were obtained by us using the regBase-CAN database)." (PMID 38396861, 2024). "It was found that two SNPs out of eight considered loci, rs10454142 PPP1R21 and rs4149056 SLCO1B1, are the likely drivers of the occurrence of tumors (“likely cancer driver”)." (PMID 38396861, 2024).
neurodevelopmental disorder (2 papers, 2023 to 2024). A behavioral and cognitive disorder with onset during the developmental period that involves impaired or aberrant development of intellectual, motor, or social functions. "Bi-allelic pathogenic variants in PPP1R21 were linked to a neurodevelopmental disorder with hypotonia, facial dysmorphism, and brain abnormalities (NEDHFBA) with pediatric onset." (PMID 36692708, 2023). "A homozygous VUS in the gene encoding Protein Phosphatase 1, regulatory subunit 21 (PPP1R21), was identified in the proband but was discounted due to dissimilarity to the phenotype associated with PPP1R21-related autosomal recessive neurodevelopmental disorders." (PMID 39469306, 2024). "Specifically, our patient’s facial gestalt was inconsistent with PPP1R21-related neurodevelopmental disorder nor did he manifest anatomic brain, cardiac, or pancreatic abnormalities, hepatosplenomegaly, optic nerve atrophy, rotatory nystagmus, or metabolic instability." (PMID 39469306, 2024).
neurodegenerative disease (1 paper, 2025). A disorder of the central nervous system characterized by gradual and progressive loss of neural tissue and neurologic function. "Polymorphisms in PPP1R21 have been previously associated with neurodegenerative diseases with numerous symptoms, including muscle weakness." (PMID 40427364, 2025).
neurologic disorders (1 paper, 2025). "Here, we have described three rare neurologic disorders resulting from mutations in either TBCK, PPP1R21, or FERRY3." (PMID 40062705, 2025). "Notably, mutations in three different members of the FERRY complex (TBCK, PPP1R21, and FERRY3) are associated with rare neurologic disorders in human patients." (PMID 40062705, 2025).
tumor (1 paper, 2017). "By real-time qPCR, we further examined the expression of selected genes (Pkm, Ppp1r13l, Vamp3, Ctnnb1, Tbc1d4, Ppp1r21, C1qtnf9, Fgf3 and Efemp2) that are known to be involved in the tumor development or potentially relevant for establishment of malignant transformation." (PMID 29073177, 2017).
PPP1R21 also shares sentences with these, for which no sentence is quoted: autosomal recessive intellectual disability (1 paper); liver carcinoma (1); lung carcinoma (1); oral cancer (1); small intestine tumor (1); stomach cancer (1).